CD4 (CD4 molecule)
Diseases named in the same sentence as CD4 in open-access papers (continued):
Sharing a sentence is not in itself a finding about the gene and the disease.
infection (continued). "To test this, we analyzed the cytokine expression profile of freshly sorted liver CD8+ and CD4+ Trm from s+16a-treated mice and untreated control mice 7 weeks after infection with Lm in a proof-of-principle experiment." (PMID 30038627, 2018). "IFN-γ producing CD4+ cells representing Th1 cells were particularly higher in response to infection of young mice with B. microti after in vitro stimulation." (PMID 30619263, 2018). "What is the expected risk of virologic failure over a long-term period if the less exposed compartment allowing the infection of new short-lived CD4 cells is responsible for the second phase of viral load decay?" (PMID 30016329, 2018). "We observed increased Tim-3 expression on splenic CD3+CD4+ Th cells (left) accompanied by a reduction in CD3+CD4+ Th cells (left) from day 3–7 post-infection in the ME49 group." (PMID 30564216, 2018). "An additional challenge for infection of resting cells by lentivectors was that quiescent CD4 + T cells fuse inefficiently with the commonly used G protein of the viral envelope vesicular stomatitis virus (VSV-G)." (PMID 29654266, 2018). "infection is a result of the host immune response and is most probably composed of CD4+ and CD8+ T cells, B lymphocytes, plasma cells and macrophages." (PMID 30236160, 2018). "Second, CD4 T cells that home to the lung after infection likely have the opportunity to interact with viral antigen bearing, class II positive antigen-presenting cells (APC) in the lung that are distinct from those in the lymph node." (PMID 29681900, 2018). "In the CSF of EAE mice on Day 6 post-infection, 5% of CD4 and almost 8% of CD8− cells were found express CD25, and approximately 25 and 42%, respectively, demonstrate high CD25 expression." (PMID 28975357, 2018). "Similar to the total CD4+ T cell compartment within P25 mice upon infection, the percentage of naive P25 transgenic CD4+ T cells decreases, while the activated population increases." (PMID 29499041, 2018). "The fate and function of CD4 T cells elicited by infection with influenza virus, although extensively studied by many groups [reviewed in Ref." (PMID 29681900, 2018). "This newer model advocates for direct infection of resting CD4+ T cells, especially in the context of lymphoid tissue or cytokine/chemokine interactions." (PMID 30285810, 2018). "We observed that depletion of CD4+ T cells rendered A129 mice susceptible to ZIKV PE243, indicating an essential role of these cells in the response to the primary infection with ZIKV." (PMID 30087337, 2018). "In contrast, CD4-depleted FVB mice treated with PBS or PBS-liposomes remained resistant to infection." (PMID 30283457, 2018). "Defined by the maintenance of normal CD4+T cells after more than 8 years of infection, these LTNPs are heterogeneous." (PMID 30687333, 2018). "In DC, T cells coculture experiment, the blockade of CD200 resulted in increased proliferation of OT-II TCR transgenic CD4+ T cells in LdWT and LdCen−/− infections." (PMID 29915577, 2018). "Following infection, splenic CD4+ T cell numbers expanded in B6.Bach2ΔT and control mice over the first 7 days of infection, but then declined over the following 7 days in B6.Bach2ΔT mice, while continuing to increase in control animals." (PMID 30459773, 2018). "Collectively, the data suggest that the rules that govern CD4+ T cell response upon immunization or infection change over the lifespan." (PMID 29864157, 2018). "CD4+ helper T cells promote effective immunity by providing the secondary signals for antibody responses and proinflammatory cytokine production upon infection." (PMID 29370185, 2018). "Though lymphotoxin (LT) is highly expressed by type I helper T (Th1) cells, its contribution to CD4+ T cell differentiation during infections and diseases remains a mystery." (PMID 30531962, 2018).
infection (continued). "For infection of CD4+ T-cells, the following mechanisms have been described: On the one hand, it is proposed that the virus is transmitted at tight cell-cell contacts via the virological synapse or via cell surface transfer of viral biofilms." (PMID 29563906, 2018). "HIV was still detected in CD14+ cervical cells 5 days post-infection, but now was also detected in CD4 T cells." (PMID 30532754, 2018). "Ag85b-specific CD4+ T cells have variable efficacy, in large part due to its reduced expression by the bacterium as early as 3 weeks after infection." (PMID 29782535, 2018). "Absolute CD4+ T cell counts also decreased after infection, but the decrease was only significant at 32 and 34 wpi." (PMID 29391069, 2018). "SVV infection also induces a marked T cell response that is characterized by an increased frequency of αβ T cells, especially CD4+ T cells that are initially detected by day 7 post-infection and increased in frequency until day 14 post-infection." (PMID 29867849, 2018). "Within the first few weeks of infection, the bulk of CD4 T-cell depletion occurs rapidly and is predominantly localized to the gastrointestinal tract." (PMID 30326919, 2018). "We place particular focus on the key role of commensal-specific CD4+ T cells in maintaining tolerance while efficiently eradicating local and systemic infections, with a focus on factors that trigger their aberrant activation." (PMID 30524431, 2018). "The greatest BMI gain occurred in patients with lower baseline CD4+ counts and higher viral load, consistent with more advanced infection." (PMID 30542325, 2018). "Large numbers of CD4+ T cells are recruited to the uterine stroma/submucosa after local infection with Chlamydia and form clusters that also include small numbers of B cells and CD8+ T cells." (PMID 29904388, 2018). "We have investigated the expression and activity of glycolytic factors in human CD4+ T cells upon activation and in response to infection with HIV-1." (PMID 29518929, 2018). "Infection of fibroblasts with human cytomegalovirus, or infection of CD4+ T lymphocytes with HIV induces an increase in HSP70 levels." (PMID 30254298, 2018). "Monocytes, total T cells, and memory CD4+ T cells were most prominent in having an inverse relationship with infection." (PMID 30444901, 2018). "The full predictive model containing number of ARS symptoms, male sex, age at infection, and enrollment CD4 and viral load had excellent performance in the overall and subtype-specific populations." (PMID 29614069, 2018). "For activated CD4+ T cells, the infected cells were cultured for 3 days and the produced viral particles were collected at days 1, 2 and 3 post infection for the ERT activity assay." (PMID 30316304, 2018). "Direct correlations were observed between CD4+ T cell activation and the percentages of IL-2-producing or ki67-expressing CD4+ T cells in patients at the acute phase of infection." (PMID 29636753, 2018). "Since we observed an impact of IL-27 on the number of antiviral CD4 T cells present upon infection, we also normalized numbers of IFNγ producing CD4 T cells to the number of polyclonal CD11a+CD49d+ antiviral CD4 T cells detected." (PMID 30044874, 2018). "In order to assess the role of CD4+ T cells in providing a CD40 stimulating microenvironment as well as in exerting immune control in vivo, we depleted these cells with a CD4 specific antibody during 3AKO and 3CKO infection." (PMID 29709016, 2018). "We also found that WT mice presented increased number of CD4+ IL-10+ T cells in LNs when compared with ST2−/− mice at the 7th day post-infection." (PMID 29867945, 2018). "We showed that T cell-specific BACH2 modulates Th2 and Th17 cell differentiation, and suppressed effector CD4+ T cell responses during infection." (PMID 30459773, 2018).
infection (continued). "Methods based on CD4 count decline and date of arrival have been used to estimate the probable country of infection and they have yielded a larger estimated proportion of post migration HIV acquisition than studies based on clinic reports." (PMID 29420591, 2018). "CD4+ T cells are among the first immune cells to arrive at the site of infection, appearing within the first 48 hours of HSV-2 infection in the epithelium." (PMID 29698393, 2018). "Yet, it is generally recognized that the early infection and irreversible destruction of CD4+ T cells in GALT is a key event in the eventual development of immune deficiencies." (PMID 29478152, 2018). "We noted a significant difference in the mortality between the CD4 depleted and control mice, where 60 percent of the depleted mice succumb to the infection compared to 100 percent survival of the control Ifnar1-/- animals." (PMID 30212537, 2018). "Our data show that early treatment of B. pertussis infected mice with AZM effectively clears the infection, but this can impair the activation of innate and adaptive immune response to B. pertussis and the induction of CD4 T cell memory." (PMID 30105030, 2018). "Both B cell and CD4+ lymphocyte activation was significantly elevated post-infection, particularly at 30 DPI." (PMID 29522489, 2018). "The ratio of CD4+T cells to CD8+T cells decreased for X4550(pYA3334-P-SspH2-EscI) infection (P < 0.05), when compared with uninfected control." (PMID 29523140, 2018). "Vaccination with the Ech_0660 mutant induces an IgG response in the serum, and a CD4 T cell response that is detectable in the peripheral blood by 7–14 days after infection." (PMID 30050533, 2018). "Investigations of the immune mechanism of RvD2 actions reveal that 6 weeks after infection, the gingiva of RvD2-treated mice exhibit decreased CD4+ T-cells as well as lower RANKL expression levels and higher osteoprotegerin expression levels." (PMID 29922275, 2018). "The L-selectin-mediated viral adhesion explains the preferential infection of central memory CD4+ T cells by HIV-1 virus." (PMID 30026537, 2018). "IFN-γ secreted by arriving CD4+ T cells triggers production of those chemokines at the site of infection, demonstrating the importance of CD4+ T cells in promoting anti-viral CD8+ T cell responses in the FRT." (PMID 29904388, 2018). "Direct correlation of activation status of infant systemic CD4+ T cells with the number of challenges to infection." (PMID 29359183, 2018). "Here we show that lamin A/C expression augments CD4+ T-cell Th1 differentiation in response to pathogen infection by regulating T-bet transcription factor expression and IFNγ production." (PMID 29311549, 2018). "Infections with H99 and the fbp1Δ mutant induced comparable CD4+ T cell activation in the MLNs, as examined by IL-2 production after ex vivo restimulation." (PMID 29317510, 2018). "Given that IL-27 promoted the numbers of antiviral CD4 T cells upon infection, and specifically M09133-147 specific CD4 T cells, we reasoned that IL-27 signaling would also help control viral replication in the salivary glands." (PMID 30044874, 2018). "In two additional samples tested at 7 days post-infection HIV was detected in CD4 T cells and still detected in CD14+ cells." (PMID 30532754, 2018). "In a murine IL-10 deficient models of infection, an increased presence of CD8+ and CD4+ T cells in inflammatory cardiac infiltrates, albeit with the exception of Treg cells, which have a decreased frequency." (PMID 30197647, 2018). "Second, it is difficult to determine the initial time and peak of infection and corresponding CD4+ T cell responses when only peripheral blood is available." (PMID 29616390, 2018). "(A) Virus-specific CD4 + or (B) CD8 +T cells were tracked in peripheral blood using MHC-tetramers after LCMV Armstrong infection (n = 8–9 mice per genotype)." (PMID 29848443, 2018).
infection (continued). "HIV disease progression consists of an acute phase where, after the initial infection, there is a peak of viral RNA and a drastic decrease of host CD4+ T cells, which can be accompanied with flu-like symptoms." (PMID 30728828, 2018). "Changes over time in the levels of mRNA and protein in activated CD4+ and resting CD4+ T cells after NL4.3‐eGFP infection were determined." (PMID 30051631, 2018). "CCR4−/− mice exhibited a lower frequency of CD4+Foxp3+ cells in the early (15 days), initial (30 days), and chronic (70 days) phases of infection than their respective WT counterparts." (PMID 30584243, 2018). "At 45 h post-infection, Smarta CD4+ T cells of both genotypes underwent two to three divisions, divided at similar rates, and showed similar levels of CD44 induction." (PMID 30575739, 2018). "Latent infection of CD4+ T cells has been attributed to blocks to elongation, distal transcription, and multiple splicing." (PMID 30316868, 2018). "We analyzed the abundance of CD32a+ CD4+ T-cell clusters in HIV+ patients in the primary-infection phase and after effective cART and compared them with those from healthy donors." (PMID 29915583, 2018). "CD4 TRM cells have also been identified in the skin after infection with Leishmania major where they persisted long after the pathogen was cleared." (PMID 30147701, 2018). "Previous reports have demonstrated that T cell influx into the lung occurs between 2 and 4 weeks postmycobacterial infection in mice, leading us to first question if l-citrulline metabolism is necessary for the early response of CD4+ T cells." (PMID 29201027, 2017). "Most of the MDSC samples (4 of 6) were positive for SIV gag and CD4, indicating infection of the MDSCs by SIVmac251." (PMID 28498847, 2017). "To determine if the increased effector functions observed for both CD8 and CD4 T cells in D2B6F1 mice contributes to their mortality, we depleted CD8 and CD4 T cells prior to Cl-13 infection." (PMID 28715493, 2017). "Nonetheless, the tropism of T/F sequences for CD4+ T cells is good evidence for this cell type being among the earliest targets for infection." (PMID 29056936, 2017). "In the submucosa, the CD4+ macrophage subset rapidly declined during the first days of acute infection; thus, the changes in the numbers of this macrophage population mirrored the changes observed in the LP." (PMID 28579989, 2017). "In consequence, at 180 days post infection, the rectal CD4 + T cell counts were more depleted in controls than in infected vaccinees (P < 0.05) and all vaccinees maintained rectal CD4 + T cell frequencies of approximately 40%." (PMID 28302457, 2017). "Joint action of Treg and Th17 cells in antimicrobial immunity was suggested by models of infection with C. albicans, in which Treg promoted differentiation of naïve CD4+ T cells into Th17 cells independently of the TGF-β-mediated tolerogenic effect." (PMID 28603524, 2017). "Following infection, CD4+ TH cells were expanded in both the liver (5x for both low and high doses) and spleen." (PMID 28851562, 2017). "In both experimental conditions, there was no apparent competitive advantage between the P2rx7-/- and B6 CD4 T cell populations that displayed similar sizes a month after infection." (PMID 28859168, 2017). "TH17 cells constitute the first subset of CD4+ T helper cells to differentiate upon exposure of antigen-presenting cells to pathogens and are therefore important during the early stages of an infection." (PMID 29295550, 2017). "While antibodies against LPS can be detected already on day 6 after the infection of C3H/HeN mice with R. conorii, specific antibodies that are generated with the help of CD4+ T cells appear relatively late in rickettsial infections." (PMID 28770333, 2017). "Through immunohistofluorescence staining and image analysis, we observed increased CD8+ T-cell numbers and stable CD4+ T-cell counts in the infected lamina propria (LP) during hyperacute infection." (PMID 28579989, 2017).
infection (continued). "No change in percentage or absolute number was observed in Foxp3+ CD4+ T cells from one to six days after infection." (PMID 28474504, 2017). "CD4 T cells isolated from the spleen of infected animals showed a considerable decrease in their proliferation during the acute phase of infection compared to CD4 T cells from control animals." (PMID 28114324, 2017). "CD4 T cell responses, especially Th1 cells, have been a primary defense force to eradicate bacteria and eliminate the infection." (PMID 29552679, 2017). "During late infection (>8 weeks postinfection), the CD4+ T cells, γδ T cells, and CD8+ T cells all tend to have reduced cytokine-producing abilities (33, –, 37)." (PMID 28507072, 2017). "We therefore opted to only reclassify as advanced infections those patients with a CD4 count of less than 100 cells/mm3 that are considered as recently infected by BED CEIA only." (PMID 29187159, 2017). "Ce taux bas de CD4+, retrouvé dans notre étude témoigne du dépistage tardif de l'infection à VIH dans nos régions." (PMID 28748017, 2017). "CCL2 is a chemoattractant for CD4+ T cells, monocytes/macrophages, and NK cells, recruiting them to the sites of infection and inflammation." (PMID 29085362, 2017). "C3H/HeN mice depleted of CD8+ T cells died upon infection with a normally sublethal dose of R. conorii while CD4+ T cell-depleted animals showed a similar course of illness as control mice." (PMID 28222146, 2017). "When we examined the frequency of CD4+Foxp3+ Tregs, we found that in contrast to pre-infection, Treg frequency was significantly reduced in Mavs−/− mice after WNV infection as compared to WT controls." (PMID 28094802, 2017). "By flow cytometry, we observed that infection with L. infantum promoted a significant induction of IFN-γ-producing CD4+ T cells in both BALB/c and A2AR−/− mice compared to their counterparts in terms of both percentages and total number of cells." (PMID 28775724, 2017). "This idea is further supported by the important roles of CD4 T cells in establishing heterosubtypic immunity during primary and secondary infection probably by providing the help to B cells." (PMID 29234060, 2017). "Whereas, a significant decrease in the frequency of LAG-3+ occurred in silenced CD4+ T-cells from lung compared to untreated lung-derived T-cells at 24h (5-fold) and 48h (3-fold) post-infection." (PMID 28880895, 2017). "Unvaccinated controls exhibited a rapid reduction of CD4 + T cells within the first few weeks of acquisition of infection." (PMID 28302457, 2017). "An explanation for the difference between the kinetics of the primary and the secondary CD4+ T cell responses is that the TCRs elicited by vaccination differ from those elicited by infection." (PMID 29176787, 2017). "Although cells other than CD4+ T cells can produce these cytokines, these data prompted us to examine their expression in purified CD4+ T cells during the course of infection." (PMID 28103263, 2017). "In these studies, CD4 perforin expression not only contributed to recovery and viral control following infection but exerted selective pressure leading to viral escape mutations." (PMID 28167943, 2017). "Surprisingly, the population of CD4+ T cells slightly declined 7 days after the second infection (D35pi) but increased 15 days later (D42pi)." (PMID 28662714, 2017). "We chose a 10:1 ratio of pRBC to DC (Fig EV1A), and we focused on day 6 post‐infection (corresponding to ECM onset) since the parasite‐specific CD4 T‐cell response was maximal at this time point and the mice succumbed beyond this day (Fig EV1B and C)." (PMID 28935714, 2017). "This association of CK level with the development of AKI remained significant after adjusting for age, sex, viral load, CD4 cell count, and presence of infection." (PMID 28716131, 2017).